Y_RNA (Y RNA )
Gene: Miscellaneous RNA gene on chromosome 14 (58,441,844 to 58,441,992, forward strand). Ensembl gene ENSG00000252198.
Homologues: Paralogues in human: Y_RNA (46% identical), Y_RNA (44% identical), Y_RNA (43% identical), RNY1P2 (42% identical), Y_RNA (42% identical), Y_RNA (41% identical), Y_RNA (40% identical), Y_RNA (36% identical), Y_RNA (34% identical), RNY1 (34% identical), Y_RNA (33% identical), Y_RNA (32% identical), and 73 more.